BRCA2 (BRCA2 DNA repair associated)
Diseases named in the same sentence as BRCA2 in open-access papers (continued):
Sharing a sentence is not in itself a finding about the gene and the disease.
non-small cell lung carcinoma (14 papers, 2011 to 2025). A group of at least three distinct histological types of lung cancer, including non-small cell squamous cell carcinoma, adenocarcinoma, and large cell carcinoma. "Nevertheless, due to their often-observed high mutational burden (e.g., due to smoking), about 5–10% of non-small cell lung cancer cases show somatic mutations in either the BRCA1 or BRCA2 gene." (PMID 34145376, 2021). "A case of non-small cell lung cancer had a BRCA2 variant detected but reported as a VUS on the TGP." (PMID 41465149, 2025). "Non-small-cell lung cancer (NSCLC) is known to demonstrate somatic alterations in BRCA1 or BRCA2 gene." (PMID 36577523, 2022). "We characterized the transcriptome of BRCA2-deficient cells, using a doxycycline (DOX)-inducible shRNA to inhibit BRCA2 expression in human non-small cell lung carcinoma H1299 cells and invasive ductal breast cancer MDA-MB-231 cells." (PMID 31316060, 2019). "Case report: complete response lasting for 10+ years in a BRCA2 carrier, whose advanced non-small cell lung cancer was treated by the combination of mitomycin C, cisplatin and vincristine." (PMID 21819606, 2011).
osteosarcoma (14 papers, 2011 to 2025). A usually aggressive malignant bone-forming mesenchymal neoplasm, predominantly affecting adolescents and young adults. "The authors concluded that the data provide evidence that RB1 status is a predictor of single-agent PARPi sensitivity in osteosarcoma-derived cells, with sensitivity levels comparable to that of BRCA2-mutated cancer cells." (PMID 37373240, 2023). "PARP1, γH2AX, BRCA1, and BRCA2 are found in the nuclei of osteosarcoma tumours, and poor survival in osteosarcoma patients has been linked to expression of these factors." (PMID 32961800, 2020). "The expression patterns of PARP1, γH2AX, BRCA1, and BRCA2 were significantly associated with shorter survival of osteosarcoma patients." (PMID 29784019, 2018). "A recent sequence analysis of the exome of osteosarcomas reported increased incidence of BRCA2 mutations as well as signatures associated with BRCA2 loss suggesting the involvement of BRCA2 in the development of osteosarcomas." (PMID 27490902, 2016). "Because the individual and combined expression patterns of PARP1, γH2AX, BRCA1, and BRCA2 were significantly associated with advanced clinicopathologic factors and survival of osteosarcoma patients, we evaluated the effects of PARP inhibition on the survival of osteosarcoma cells." (PMID 29784019, 2018). "In clinical tissue samples, the expression of PARP1, γH2AX, BRCA1, and BRCA2 were closely associated with each other and their expression patterns were correlated with advanced clinical indicators of osteosarcoma such as higher stage, latent distant metastasis, and higher histological grade." (PMID 29784019, 2018). "Both yielded significantly increased median sensitivity for the RB1-defective compared to the RB1-normal osteosarcoma group, with sensitivities across the RB1-defective group greater than, or closely matching that of BRCA2-mutated CAPAN1." (PMID 34862364, 2021). "Collectively the data provide evidence that RB1 status is a predictor of single-agent PARPi sensitivity in osteosarcoma, with sensitivity levels comparable to that of BRCA2-mutant cells." (PMID 34862364, 2021). "Nevertheless, it was reported that up to 80% of osteosarcoma patient samples exhibit a “BRCAness,” indicating that they share similarities to tumours harbouring germline mutations in BRCA1 or BRCA2 making them deficient in DNA repair pathways." (PMID 32961800, 2020). "The expression of PARP1, γH2AX, BRCA1, and BRCA2 were grouped as positive in 74% (26 of 35 of cases), 57% (20 of 35 of cases), 49% (17 of 35 of cases), and 46% (16 of 35 of cases) of osteosarcomas, respectively." (PMID 29784019, 2018). "The variables included in multivariate analysis for the 35 osteosarcomas were the factors significantly associated with OS or RFS: age, tumor size, tumor stage, distant metastasis, histologic grade, and the expression of PARP1, γH2AX, BRCA1, and BRCA2." (PMID 29784019, 2018). "Therefore, this study evaluates the expression and prognostic significance of the individual and combined expression patterns of PARP1 and PARP1-related DDR molecules such as γH2AX, BRCA1, and BRCA2 in osteosarcomas." (PMID 29784019, 2018). "In conclusion, this study demonstrated that the individual and combined expression patterns of PARP1, γH2AX, BRCA1, and BRCA2 might be useful for the prediction of survival of osteosarcoma patients." (PMID 29784019, 2018). "Moreover, when we performed addition analysis on the combined expression patterns of PARP1, γH2AX, BRCA1, and BRCA2, 51% (18/35) of osteosarcomas were included in the poor-prognostic group." (PMID 29784019, 2018). "A single case of osteosarcoma in a patient with a germline Brca2 mutation has been reported, but the association has not been investigated further." (PMID 21403899, 2011).
osteosarcoma (continued). "The onset of the disease may be related to deletion in the BRCA1 and BRCA2 genes, which led to the inability of cells to effectively repair DNA damage, resulting in genomic instability that promoted the occurrence and progression of osteosarcoma." (PMID 40104509, 2025). "Similarly, amplifications of MYC, BRCA2, and a co‐amplification of the region PDGFRA–KIT occurred mostly in recurring tumors (P1, P2, P4, P6, P7, P10), whereas JUN and APC mutations occurred in a single osteosarcoma primary (P1)." (PMID 33963544, 2021). "Herein, we describe the case of a 28-year-old man diagnosed with the primary cutaneous osteosarcoma with decreased copy number of BRCA1 and BRCA2, based on histological morphology, immunohistochemical examination, and germline testing." (PMID 40104509, 2025). "Our data also explain why a BRCA2-derived peptide that targets RAD51 function elicited olaparib-induced cell death of U2OS human osteosarcoma cells but not of noncancerous cell lines." (PMID 35969531, 2022). "Notably, median sensitivities closely matched that for BRCA2-mutated, cisplatin-hypersensitive CAPAN140, indicating high platinum sensitivity across osteosarcoma lines, irrespective of status and PARPi sensitivity." (PMID 34862364, 2021). "Consistent with this, one study showed that osteosarcoma cell lines with BRCAness (MG-63, ZK-58, Saos-2, and MNNG-HOS) were sensitive to the PARP1 inhibitor talazoparib, while a cell line with a heterozygous BRCA2 mutation (U2-OS) was not." (PMID 32961800, 2020).
skin cancer (14 papers, 2002 to 2026). "We estimated the annual and cumulative risk of skin cancer in women who carry BRCA1 or BRCA2 mutations." (PMID 38741145, 2024). "We found 38 studies reporting 122,209 cases investigating BRCA2 gene variants in different cancer types including breast, ovarian, pancreatic, lung, upper aero-digestive system, urinary tract and skin cancers." (PMID 33672545, 2021). "It is likely that factors including reproductive characteristics, lifestyle and genetic predisposition such as BRCA2 play a more important role in the excess risk of both second breast and skin cancer after BCIS." (PMID 16804522, 2006). "BRCA2 changes have also been related to other aggregations of malignancy, which include predispositions to ovarian, pancreatic or skin tumours." (PMID 12373604, 2002). "However, environmental factor-associated cancers (lung and skin carcinoma) were more frequent in families of the BRCA2 c.9976A>T carrier probands." (PMID 33672545, 2021). "However, as suggested by other authors, patient carriers of a BRCA1/BRCA2 mutations should be informed about the risk of skin cancer and be subjected to a periodic dermatological control." (PMID 29346284, 2018). "The cumulative risk of all types of skin cancer from age 20 to 80 years was 14.1% for BRCA1 carriers and 10.7% for BRCA2 carriers." (PMID 38741145, 2024). "Women from the United States had a higher risk of skin cancer than those from Canada (HR = 1.98, 95% CI: 1.39, 2.83, p < 0.0001) for BRCA1 carriers and HR = 1.55 (95%CI 1.04–2.30; p = 0.03) for BRCA2 carriers." (PMID 38741145, 2024). "We estimated the cumulative risk of any skin cancer from age 20 to 80 to be 14.1% for BRCA1 mutation carriers and 10.7% for BRCA2 mutation carriers." (PMID 38741145, 2024). "Overall, between age 40 and 79 the annual risk for any skin cancer was 0.5% for BRCA1 carriers and 0.6% for BRCA2 carriers." (PMID 38741145, 2024). "We found the cumulative risk of all types of skin cancer reported in this cohort from age 20 to 80 years to be 14.1% for BRCA1 mutation carriers and 10.7% for BRCA2 mutation carriers." (PMID 38741145, 2024). "A previous diagnosis of skin cancer was reported by 3.4% of BRCA1 mutation carriers and by 4.1% of BRCA2 mutation carriers." (PMID 38741145, 2024). "Similarly, whether the skin site was chronically exposed to UV radiation or not did not affect skin cancer detection in BRCA2, CHEK2, or CHEK2 1100delC pathogenic variant carriers." (PMID 41331641, 2025). "Future studies will be conducted to better estimate the lifetime cumulative rate of skin cancer among BRCA1 and BRCA2 carriers." (PMID 38741145, 2024).
diabetes (13 papers, 2014 to 2025). "We identified 160 variants in BRCA1 and 274 variants in BRCA2 based on the analysis of 3842 Mexican population samples from the SIGMA Diabetes database." (PMID 30630528, 2019). "In conclusion, the association between metabolic disorders, including diabetes and the metabolic syndrome, and BRCA1 and BRCA2 mutations is of major clinical relevance and warrants further investigation." (PMID 35432218, 2022). "However, diabetes may induce “BRCAness” by an alternative mechanism involving loss of gene expression, since BRCA1 and BRCA2 transcripts were commonly downregulated in the clinical samples and xenografts in the presence of diabetes." (PMID 37906280, 2023). "Moreover, the application of TATA-box-targeting siRNAs to specifically activate some important genes, such as insulin, tumor repressor genes (p21) or DNA repair genes (BRCA2), may provide a new safe treatment strategy for many diseases such as cancer and diabetes." (PMID 25250958, 2014).
esophageal cancer (13 papers, 2011 to 2025). A primary or metastatic malignant neoplasm involving the esophagus. "The results of this large-scale registry-based study suggest that pathogenic variants in BRCA1 and/or BRCA2 are associated with increased risk of biliary tract, gastric, and esophageal cancers." (PMID 35420638, 2022). "Pathogenic variants in BRCA2 were associated with increased risk of 7 cancer types: female breast, gastric, ovarian, male breast, pancreatic, prostate, and esophageal cancers." (PMID 35420638, 2022). "In the TCGA WES esophageal cancer cohort, a BRCA2 deficient case demonstrated an HRD score ≥42." (PMID 38589664, 2024). "Although there is a well-documented role for alcohol consumption in susceptibility to esophageal cancer, such individuals are expected to be more vulnerable to ESCC risk due to the aldehyde-induced BRCA2 haploinsufficiency model." (PMID 37943872, 2023). "In addition, the family with lung and esophageal cancers, two VUS BRCA2 and MRE11A mutations were detected in two BC patients with BRCA1 likely pathogenic mutation." (PMID 30982232, 2019). "However, the identified candidate genes within this region, such as RB1, BRCA2, and ING1, seldom show mutations in esophageal cancer, implying that other unknown tumor-suppressor genes within this region might participate in the tumorigenesis of this cancer." (PMID 22174605, 2011). "The father of the patient with BRCA2 c.6468_6469delTC/BIC: 6696delTC had laryngeal cancer, and the brother and father of the carrier of PV BRCA1 c.2498delT had gastric and esophageal cancer." (PMID 37791908, 2023). "LOH and MSI frequencies were evaluated at chromosomal regions known to be frequently altered in sporadic esophageal cancer with particular attention to loci nearby genes involved in DNA double strand break (DSB) or in the oxidative damage repair pathways (i.e. BRCA1, BRCA2, RAD1 and MSRA)." (PMID 25611972, 2015). "In addition, the synergistic effects of FHIT, BRCA2, MLH1, and other related factors may be the molecular basis of esophageal cancer." (PMID 40539057, 2025).
leiomyosarcoma (13 papers, 2016 to 2025). An uncommon, aggressive malignant smooth muscle neoplasm, usually occurring in post-menopausal women. "One additional patient with uterine leiomyosarcoma had a pathogenic BRCA2 mutation, but the HRD score was low." (PMID 40144205, 2025). "A separate study found that BRCA2 mutations were present in 17% of leiomyosarcoma." (PMID 40563612, 2025). "In the accompanying genomic analysis, an enrichment of BRCA2 somatic alterations were observed among uterine leiomyosarcoma, confirming their prevalence and potential clinical actionability." (PMID 38716772, 2024). "Homozygous deletions of BRCA2 were present in 5% of uterine sarcoma patients in another study and evidence of clinical benefit in patients with uterine leiomyosarcoma with somatic BRCA2 alterations treated with PARP inhibitors has been described." (PMID 39329869, 2024). "This Molecular Tumor Board report describes a remarkably response achieved with the use of Niraparib in a patients affected by uterine leiomyosarcoma carrying a somatic biallelic BRCA2 alteration." (PMID 38716772, 2024). "One patient (1.4%) with leiomyosarcoma that was HRD+ and had a germline BRCA2 mutation experienced confirmed CR, seven patients (10.1%) achieved PR, and 32 patients (46.4%) had SD." (PMID 38970256, 2024). "The expression of BRCA2 mRNA was higher in dedifferentiated liposarcoma (n = 46), myxofibrosarcoma (n = 31) leiomyosarcoma (n = 26), pleomorphic liposarcoma (n = 23), and malignant fibrous histiocytoma (n = 9) compared with normal tissue." (PMID 27643881, 2016).
colorectal adenocarcinoma (12 papers, 2016 to 2025). The most common type of colorectal carcinoma. "As previously reported, we also found ART558 to be effective in decreasing cell viability and colony formation in DLD1 colorectal adenocarcinoma cells with a truncating mutation in BRCA2 compared with isogenic WT DLD1 cells." (PMID 36976649, 2023). "To address this, we generated xenografts in CB17‐SCID mice using the isogenic BRCA2+/+ (BRCA2‐proficient) and BRCA2−/− (BRCA2‐deficient) human colorectal adenocarcinoma DLD1 cells." (PMID 35107878, 2022). "Herein, we show that BRCA2 is inactively mutated in 10% of gastric and 7% of colorectal adenocarcinomas, and that this inactivation is significantly correlated with microsatellite instability." (PMID 32980867, 2020). "In human DLD1 colorectal adenocarcinoma cells, DNA combing analysis revealed that acetaldehyde causes replication stress especially in the absence of BRCA2." (PMID 34328261, 2021). "The HER2-TTC/PARPi combination was evaluated on colorectal adenocarcinoma HER-2 positive cell line DLD-1 parental and DLD-1 BRCA2 −/− with an inactivation of BRCA2, a gene involved in DNA DSBs repair." (PMID 34207408, 2021). "In addition, we utilized a BRCA2 knockout human colorectal adenocarcinoma cell line, DLD1 BRCA2 (−/−), which is known to be highly sensitive to PARP inhibition compared to parental cells retaining BRCA223,24." (PMID 32444794, 2020). "The in vitro combination effect of HER2-TTC and PARPi olaparib was evaluated on the colorectal adenocarcinoma cell line DLD-1 parental and DLD-1 BRCA2 -/- Firstly, we determined the expression of HER2 antigens on the surface of the cell lines by flow cytometry." (PMID 31618864, 2019). "To investigate whether PDS-induced G4 stabilization affects viability of human cells lacking BRCA2, we used a matched pair of BRCA2-proficient and deficient DLD1 colorectal adenocarcinoma cell lines." (PMID 26748828, 2016).
ductal carcinoma (12 papers, 2008 to 2025). "The BRCA2 variant NM_000059.4:c.2471T>G was identified in a 61 year-old patient that was diagnosed with bilateral breast ductal carcinoma at the age of 44." (PMID 39796670, 2024). "BRCA1 (n = 5) and BRCA2 (n = 5) were the most frequently mutated genes, as commonly reported in ductal breast carcinoma." (PMID 38308423, 2024). "We describe the parental origin and functional characterization of a novel de novo BRCA2 splice site mutation found in a patient exhibiting a ductal carcinoma at the age of 40." (PMID 18597679, 2008). "The BRCA2 variant NM_000059.3:c.8331+1G>A was identified in a 52-year-old patient that was diagnosed with bilateral BC at the ages of 39, with lobular carcinoma in the right breast, and 47, with ductal carcinoma in the left breast; both were PR and ER positive and HER2 negative." (PMID 39796670, 2024). "Similarly, ductal carcinomas were more frequent in BRCA1 carriers (p < 0.05), while tumors of mixed histology were significantly associated with BRCA2-positive tumors (p < 0.05)." (PMID 39001430, 2024). "The BRCA2 mutations were more prevalent in lobular (7/62; 11%) than in ductal carcinomas (20/348; 6%); again, differences were not statistically significant." (PMID 19232099, 2009). "The histological subtypes were not significantly different between groups (p = 0.495), with most of the patients having a ductal carcinoma (59.3%—BRCA-negative group; 50%—BRCA1 group; 63.6%—BRCA2 group)." (PMID 41002733, 2025). "Finally, as expected, most of hereditary luminal-like EOBCs were BRCA2-associated and HER2/neu-negative, and all of them were to be accounted for as ductal carcinoma." (PMID 32429297, 2020).
thyroid cancer (12 papers, 2012 to 2025). "We analyzed the relationship between single-nucleotide polymorphisms (SNPs) in BRCA1 and BRCA2 and thyroid cancer and conducted a haplotype analysis of these polymorphisms to study the interactions between genetic polymorphisms." (PMID 40361383, 2025). "Abnormal expression of BRCA2 is associated with various types of malignancies, such as breast cancer, ovarian cancer, and thyroid cancer." (PMID 38892180, 2024). "Thyroid cancer (TC) has also been associated with the presence of germline mutations in BRCA2 and ATM genes." (PMID 38890714, 2024). "The discovery of altered mRNA secondary structure and reduced BRCA2 expression suggests that this polymorphism may affect the function of this gene, which may have implications for the development of thyroid cancer." (PMID 38892180, 2024). "A study of a Chinese ethnic population evaluated the association of SNPs in the 3′-UTR double-strand break repair genes RAD51, RAD51B, BRCA1 (rs12516, rs8176318), BRCA2 (rs15869), XRCC4, and XRCC5 with the risk of thyroid cancer in 206 patients with PTC." (PMID 40361383, 2025). "The association of BRCA1 and BRCA2 mutations with thyroid carcinoma has not been well evaluated." (PMID 40361383, 2025). "BRCA1 and BRCA2 mutations do not increase thyroid cancer incidence." (PMID 34577828, 2021).